STMND1 (stathmin domain containing 1)
Synonyms: FLJ23152
Tractability: No criterion of Open Targets' tractability assessment is met for any kind of drug.
Gene: Protein-coding gene on chromosome 6 (17,102,050 to 17,131,378, forward strand). Ensembl gene ENSG00000230873.
Subcellular location (Human Protein Atlas): Actin filaments
Gene Ontology:
Molecular function: tubulin binding
Biological process: microtubule depolymerization; neuron projection development; regulation of microtubule polymerization or depolymerization
Cellular component: cytoplasm; neuron projection
Genetic constraint (gnomAD): Loss-of-function variants: 18 observed, 23.3 expected, observed/expected ratio (o/e) 0.77, 90% interval 0.53 to 1.15. The upper end of that interval is the gene's LOEUF score, 1.15, which puts it in group 5 of 6, group 1 being the genes least tolerant of losing a copy. Missense variants: 300 observed, 337.61 expected, observed/expected ratio (o/e) 0.89, 90% interval 0.81 to 0.98. Synonymous variants: 112 observed, 121.97 expected, observed/expected ratio (o/e) 0.92, 90% interval 0.79 to 1.07.
Homologues: Orthologues: chimpanzee STMND1 (96% identical), macaque STMND1 (92% identical), mouse Stmnd1 (67% identical), rat Stmnd1 (67% identical), dog STMND1 (66% identical), guinea pig STMND1 (64% identical), rabbit STMND1 (63% identical), pig STMND1 (61% identical), tropical clawed frog STMND1 (35% identical), zebrafish stmnd1 (26% identical), Drosophila melanogaster stai (15% identical). Paralogues in human: STMN4 (17% identical), STMN3 (16% identical), STMN2 (16% identical), STMN1 (14% identical).
Diseases named in the same sentence as STMND1 in open-access papers:
STMND1 is named in the same sentence as 1 disease in open-access papers, as found by Europe PMC text mining. Sharing a sentence is not in itself a finding about the gene and the disease. The quoted sentences say what the papers report.
Stroke (1 paper, 2020). Sudden impairment of blood flow to a part of the brain due to occlusion or rupture of an artery to the brain. "STMND1 (Stathmin Domain Containing 1) Variants in STMND1 have been associated with stroke in African Americans, though rs927629 has not been previously reported with CVD." (PMID 33171725, 2020).